SMIM48 (small integral membrane protein 48)
Gene: Protein-coding gene on chromosome 17 (5,499,427 to 5,501,006, reverse strand). Ensembl gene ENSG00000286190.
Subcellular location: Endoplasmic reticulum membrane
Gene Ontology:
Cellular component: endoplasmic reticulum membrane
Genetic constraint (gnomAD): Loss-of-function variants: 4 observed, 3.29 expected, observed/expected ratio (o/e) 1.21, 90% interval 0.56 to 1.9. That is too few expected variants to judge how well the gene tolerates losing a copy. Missense variants: 158 observed, 126.87 expected, observed/expected ratio (o/e) 1.25, 90% interval 1.09 to 1.42. Synonymous variants: 81 observed, 62.04 expected, observed/expected ratio (o/e) 1.31, 90% interval 1.09 to 1.57.
Homologues: Orthologues: mouse 6330403K07Rik (73% identical), rat 6330403K07Rikl (73% identical).